MET (MET proto-oncogene, receptor tyrosine kinase)
Diseases named in the same sentence as MET in open-access papers (continued):
Sharing a sentence is not in itself a finding about the gene and the disease.
glioblastoma (continued). "It is shown that in a preclinical setting MET inhibition with RTK inhibitors is effective and MET fusion positive pediatric glioblastoma respond positively before relapse." (PMID 35169893, 2022). "IKK16 also abrogates resistance of glioblastoma U87MG cells to the Gefitinib+PHA665752 (a MET inhibitor) treatment via blocking fibroblast growth factor 1 (FGF1) expression." (PMID 36358633, 2022). "MIR562 has been shown to reduce the expression of c-MET in glioblastoma cells by directly binding to its 3’-UTR20." (PMID 34620846, 2021). "Capmatinib was confirmed to be effective for treating multiple cancers, such as patients with c-MET-dysregulated advanced solid tumors, glioblastoma, HCC, NSCLC, and colorectal cancer." (PMID 34804015, 2021). "MiR-128-3p targeting c-MET inhibited glioblastoma migration and invasion and enhanced TMZ therapeutic efficacy in vivo." (PMID 34532286, 2021). "Other miRNAs such as miR-34a, miR-144-3p, and miR-562 have been reported to exert activity against glioblastoma proliferation and invasion by also targeting c-MET." (PMID 34532286, 2021). "In patient-derived glioblastoma cells, VEGF blockage restores MET activity, and c-MET inhibition decreases the invasive capacity of glioblastoma cells." (PMID 33916438, 2021). "MET signaling remains a critical pathway in glioblastomas, but thus far akin to other molecular targets therapeutics targeting of MET fell rather short of expectations." (PMID 32258244, 2020). "Blockage of VEGF-A in glioblastoma has been shown to increase MET activity in a hypoxia-independent manner, in turn, enhancing tumor invasion." (PMID 32587778, 2020). "In the context of the experimental glioblastoma microenvironment, miR-1 directly targets annexin A2 and the proto-oncogene MET, and miR-1-loaded extracellular vesicles lead to diminished invasion and proliferation in targeted cells." (PMID 32258065, 2020). "For example, higher Sema3C levels in castration-resistant prostate cancer cells as well as in glioblastoma U87, bladder T24, and kidney Caki-2 cells activated phosphorylation of MET and EGFR, in a dose-dependent manner." (PMID 31726800, 2019). "Further molecular testing illustrated features more consistent with glioblastoma: multiple large chromosomal aberrations including loss of whole chromosome 1 and 2q; gain/amplification of MYCN, MET, and CDK4; loss of CDKN2A/B; and an ATRX mutation." (PMID 30738431, 2019). "In order to verify our conjecture, we detected the protein level of MET, which is an important oncogene in glioblastoma." (PMID 31349699, 2019). "Multiple genes implicated in cell proliferation and differentiation, including the telomerase reverse transcriptase gene, c-MET, EGFR and NF1, have been showed to be mutated or overly expressed in glioblastoma." (PMID 30787206, 2019). "We have used fluorescence-tagged antibodies to activate MET in live serum-starved glioblastoma cells and monitor the fate of antibody-bound MET receptor in single cell-based assays." (PMID 30760737, 2019). "Levels of EGFR and MET expression in glioblastomas were inversely correlated (Spearman R = -0.59, p < 0.0001)." (PMID 31747973, 2019). "It is possible that the binding of MET with antibodies altered the highly efficient recycling pathway for MET proteins in glioblastoma cells, leading to degradation of the receptor proteins." (PMID 30760737, 2019). "We first assayed the effects of the anti-MET antibodies on cancer cell invasion when glioblastoma cells were cultured in the complete media." (PMID 30760737, 2019). "In glioblastoma CSCs, the autophagy-associated factors DRAM1 and p62 were highly expressed, and subsequent activation of mitogen-activated protein kinase and c-MET had a role in cell migration and invasion." (PMID 30166520, 2018). "In glioblastoma, gastric and head and neck tumors expressing both c-Met and HGF, the mutation of MET was found and correlated with poor prognosis in patients." (PMID 29455657, 2018).
glioblastoma (continued). "In this study we investigated ALK, ROS1, and MET status in nine glioblastoma stem cell lines and tumors from which they arise." (PMID 28960893, 2017). "Other dual-therapy regimens being examined are combined inhibition of AKT/mTOR and MDM2 in glioblastoma, and combined c-MET and EGFR in non-small lung cancer." (PMID 26955870, 2016). "PV-O glioblastomas were associated with lower expression of VEGFC (p = 0.032) than other periventricular locations, whereas MET overexpression remained exceptional." (PMID 26637806, 2016). "c-MET is widely expressed in human cancers and also in CSCs isolated from different tumors such as glioblastoma, head and neck carcinoma, pancreatic and colorectal cancer." (PMID 27322553, 2016). "A similar pattern of c-MET increase was also reported in patients with progressive/recurrent glioblastoma treated with cabozantinib in a phase 2 trial and in a single-institution subset of patients from this mCRPC patient cohort." (PMID 26762579, 2016). "These authors demonstrated that c-MET activation is inhibited in glioblastoma cells that also express VEGFR2 in the presence of VEGF." (PMID 23484006, 2013). "Amplification of the c-MET gene (located on chromosome 7) is seen in glioblastomas and both c-MET and HGF are frequently overexpressed in glioma specimens and cell lines." (PMID 23484006, 2013). "Glioblastoma initiating cells have evolved the ability to activate c-MET and NOTCH pathways after IR, highlighting the cunning ways by which GICs overcome standard cytotoxic treatment." (PMID 23579692, 2013). "The proposed functional role of c-MET in tumor cell migration makes this receptor an attractive therapeutic target in c-MET positive glioblastoma." (PMID 23484006, 2013). "Inhibition of MET signaling in glioblastoma stem cells (GSC) disrupts tumor growth and invasiveness both in vitro and in vivo, suggesting that MET activation is linked to cancer stem cell phenotype." (PMID 23109895, 2012). "The HGF/SF:c-MET signaling axis has an important role in the initiation and progression of several aggressive cancers including glioblastoma multiforme (GBM)." (PMID 22511956, 2012). "Of interest, it has recently been shown that the MET receptor activating phosphorylation site was highly responsive to EGFRvIII levels in glioblastoma cells in vitro, suggesting downstream cross-activation of MET by mutant EGFRvIII." (PMID 19238632, 2008). "Analysis of tissue sections from DBM2 tumors for human c-MET and uPAR expression pinpointed the location of invasive glioblastoma cells in the brain parenchyma and at the same time examined an important mechanism for cellular invasion." (PMID 19055779, 2008). "Furthermore, expression of several genes associated with glioblastoma (STAT3, PDGFRA, MET, and NF1) and neuroblastoma (GATA3, ISL1, LMO1, and LIN28B) progression was downregulated at the transcriptional level in differentiated cells." (PMID 39859209, 2025). "Several small-molecule inhibitors have emerged to target oncogenic MET aberrations in glioblastoma." (PMID 39518074, 2024). "Antibodies targeting c-MET have been shown to decrease the growth of glioblastoma cells and may show promising results compared to angiogenic therapies." (PMID 38892305, 2024). "Another pathway involved with EC expression in glioblastomas is the c-MET pathway." (PMID 38892305, 2024). "In a cohort of 53 pediatric glioblastomas, 10% harbored MET oncogenic fusions." (PMID 39409964, 2024). "The high expression of c-MET could even predict a poor prognosis in glioblastoma patients receiving anti-PD1 treatment." (PMID 38352883, 2024). "Cabozantinib, an MET inhibitor, was moderately active in individuals with recurrent glioblastoma." (PMID 37077370, 2023). "This could be important, since the activation of the c-MET/TrkA-B pathways was described as being involved in therapeutic resistance of glioblastoma to CDK4/6i, and c-MET inhibition with altiratinib in combination with CDK4/6i can be effective in this setting." (PMID 37835528, 2023).
glioblastoma (continued). "MET expression has in fact been proposed as a marker for stemness in glioblastoma." (PMID 36915128, 2023). "Indeed, the RTK c-MET has been widely studied in tumors resistant to anti-VEGF therapy and associated to worst prognosis in glioblastoma patients treated with BEVA." (PMID 37041632, 2023). "In addition, TBMS I also increases the ubiquitination level of protooncogene (MET) to decrease the protein level of MET, thereby repressing the abnormal activation and amplification of MET, and ultimately inhibiting the proliferative activity of glioblastoma." (PMID 36160391, 2022). "Furthermore, because ZM fusion genes are frequently found in secondary glioblastomas with poor prognosis and higher MET activity, clinical trials of MET kinase inhibitors have been recently initiated." (PMID 35457233, 2022). "This initial data promotes further research with MET inhibitors in pediatric glioblastomas." (PMID 35169893, 2022). "MET is commonly overexpressed or amplified in human glioblastoma." (PMID 33435218, 2021). "Our studies suggest that development of bivalent anti-MET immuno-reagents may hold a promise to target and remove the MET proteins from glioblastoma cells or other cancer cells that possess high HGF-induced recycling activity of MET." (PMID 30760737, 2019). "To determine whether the activation of MET by these conjugated antibodies is not limited to human U373-MG glioblastoma cells, we also tested the response of other human glioblastoma cell lines, such as T98G, LN229, and LN18." (PMID 30760737, 2019). "In consequence, targeting ITGA5 or MET genes could inhibit the invasive capacity of glioblastoma cells induced by low RND1 expression and especially the one of PVZ+ cells." (PMID 30333910, 2018). "Finally, combined treatment with BH3-mimetics and c-MET inhibitors results in significantly smaller tumors than each treatment alone in a PDX model system of glioblastoma." (PMID 29743557, 2018). "Interestingly, a patient with a pediatric glioblastoma harboring a MET fusion was treated with the targeted inhibitor, resulting in transient tumor shrinkage." (PMID 30279357, 2018). "Moreover, VEGF was reported to negatively regulate c-MET activation, resulting in the direct suppression of tumor invasion in a mouse model of glioblastoma." (PMID 29670046, 2018). "Of these, the HGF/cMET pathway has seemed an attractive target as it has been shown to operate in many tumors, for example, preclinical studies in glioblastoma and pancreatic neuroendocrine tumor models have shown that MET inhibitors can overcome resistance to anti-VEGF therapy." (PMID 29228696, 2017). "Expression of c-MET is associated with a poor prognosis in glioblastoma, with median survival of 11.7 months compared to14.3 months in patients with lack of c-Met tumor expression." (PMID 29081735, 2017). "p-c-MET was detected in glioblastoma cells as well as in the vasculature." (PMID 29238047, 2017). "However, the functional interactions between TGF-β family members and HGF/c-MET signaling in glioblastoma remain uncharacterized." (PMID 29238047, 2017). "Accordingly, c-MET negativity could be explored as a predictive biomarker for future clinical trials exploring TGF-β inhibition in glioblastoma." (PMID 29238047, 2017). "If so, recurrent glioblastomas may be particularly vulnerable to radiosensitization strategies involving the use of MET inhibitors." (PMID 26909358, 2015). "In vivo, it delayed the growth of U87-MG human glioblastoma cells, which express both MET and HGF." (PMID 28548076, 2014). "However, it must be realized that this is only relevant for glioblastomas that are positive for both c-MET and VEGFR2." (PMID 23484006, 2013). "Targeting of c-MET may further be beneficial as signaling from this receptor may induce and maintain the glioblastoma stem cell-like phenotype and therefore resistance to chemotherapy and radiotherapy." (PMID 23484006, 2013).
glioblastoma (continued). "We therefore analyzed the effects of the c-MET- and VEGFR2 tyrosine kinase inhibitor cabozantinib (XL184, Exelixis) on c-MET positive orthotopic E98 glioblastoma xenografts, which routinely present with angiogenesis-dependent areas of tumor growth, as well as diffuse infiltrative growth." (PMID 23484006, 2013). "The signaling pathways of RTKs, including EGFR, PDGFR, and/or c-MET, are often modified throughout the pathogenesis of glioblastoma multiforme (GBM)." (PMID 38504984, 2024). "Glioblastomas (GBM), another highly lethal CNS cancer, is characterized by aberrant activation of multiple pathways, including the Hedgehog (HH) or MET (also known as c-MET, receptor tyrosine kinase for Hepatocyte Growth Factor (HGF)) signaling." (PMID 38273337, 2024). "Hence, these therapeutic miRNAs and c-MET siRNAs could be used to treat glioblastoma by means of suppressing tumor invasion and EMT." (PMID 34532286, 2021). "Contrary to the concern that bivalent antibodies may activate the targeted RTKs, in this report, we found that glioblastoma cells have an unusual high activity of HGF-induced MET receptor recycling with very few MET molecules get downregulated after HGF stimulation." (PMID 30760737, 2019). "Therefore, TBMS1 is a promising compound for the treatment of glioblastoma and an inhibitor of MET." (PMID 31349699, 2019). "Recent data suggest that glioblastomas (GBM) activate the c-MET signaling pathway and display increased levels in anti-apoptotic Bcl-2 family members." (PMID 29743557, 2018). "We have found that SEMA3C stimulates EGFR and MET signaling in a broad range of cancer cell lines including bladder, and renal cancer as well as glioblastoma, suggesting that SEMA3C may be an important growth factor for a broad spectrum of cancers in addition to PCa." (PMID 29348142, 2018). "The modulation of c-MET pathway activity by TGF-β allows to speculate that subsets of patients with glioblastoma would have responded to TGF-β inhibitors such as galunisertib (LY2157299 monohydrate) with an increase of c-MET activity and potentially MET-mediated migration and invasion." (PMID 29238047, 2017). "Simultaneous targeting of the VEGF and c-MET pathways may therefore be an interesting therapeutic approach for c-MET-positive glioblastoma because it will reduce vessel leakage (resulting in edema reduction) and simultaneously may reduce tumor cell migration and thus tumor progression." (PMID 23484006, 2013). "In this study, we uncover SPRY2-dependent bypass signaling mechanisms in glioblastoma that contribute to resistance against EGFR and MET (hepatocyte growth factor receptor) inhibition." (PMID 41567627, 2025). "RTKs including EGFR, VEGFR, PDGFR, MET, and AXL regulate essential activities such as cell proliferation, survival, invasion, and angiogenesis, enhancing glioblastoma’s resistance to standard treatments." (PMID 40332008, 2025). "Furthermore, the in-vitro experiment results indicated that the knockdown of c-MET could decrease the survival and proliferation of glioblastoma cell line ln299, which could be further enhanced by the combination treatment with cabozantinib (2μM, a c-MET inhibitor)." (PMID 38352883, 2024). "In glioblastoma, a VEGF blockade disrupts the recruitment of a MET-inhibitory phosphatase (PTP1B) to the VEGFR2–MET complex, resulting in increased MET activation and tumor invasion." (PMID 39769452, 2024). "Members of the receptor tyrosine kinase gene family including EGFR, MET, PDGFRA, and FGFR3 have been known to be heavily involved in the initiation and progression of glioblastoma." (PMID 39087020, 2024). "The mRNA expression analysis also showed that the basal expression of both MET and ST7 are very low in the glioblastoma cases, in contrast to the very high basal expression of PTPRZ1." (PMID 38254850, 2024). "In glioblastoma, most RTK driver alterations were CN gains/amplifications, accounted for by EGFR, PDGFRA, and to a lesser extent, MET." (PMID 38254850, 2024).
glioblastoma (continued). "Stimulating receptor tyrosine kinases, like HGFR/c-MET, activates the Ras-Raf-MEK-ERK signaling factors, which results in glioblastoma growth." (PMID 39574474, 2024). "HGF/c-MET signaling is a significant driver of glioblastoma (GBM) growth and disease progression." (PMID 37162666, 2023). "Two patients with MET amplified and PDGFRA/KDR amplified glioblastoma were treated with cabozantinib and attained partial response." (PMID 38143440, 2023). "MET signalling is required for glioblastoma (GBM) stem cell maintenance." (PMID 37491377, 2023). "The PTPRZ1–MET fusion has been described in adult glioblastomas and entails the full length MET protein fused to the first exons of PTPRZ1 and probably uses its promoter to overexpress MET." (PMID 35169893, 2022). "Early studies of human primary brain tumor samples have shown increased expression of c-MET and/or HGF in higher grade gliomas, such as glioblastoma multiforme (GBM)." (PMID 36034555, 2022). "Four of these seven cases relate to glioblastoma in which fusion pairs CAPZA2-MET and FIP1L1-PDGFRA, CAPZA2-MET and MET-MET, EGFR VIII and PTPRZ1-MET, PTPRZ1-MET and TBL1XR1-PIK3CA were identified." (PMID 35984852, 2022). "This trial reports for the first time that the addition of crizotinib, an ALK, ROS1, and c-MET inhibitor, to standard RT and TMZ is safe and resulted in a promising efficacy for newly diagnosed patients with glioblastoma." (PMID 35625997, 2022). "In the M6 prolactinoma, MET was the only RTK with relative high overexpression, although the absolute levels were average in comparison to other CNS tumors, such as glioblastoma." (PMID 35978432, 2022). "The genes most involved in fusions in IDH wild-type glioblastoma are EGFR (6–13%), FGFR3 (3%), MET (1–4%) and the NTRK gene family (1–2%)." (PMID 36002559, 2022). "Amongst the genes down-regulated by miR-34a, we selected five genes (ATM, EGFR, BCL2, MET, UGCG) for validation as they have been shown pre-clinically to play critical roles in cell survival and therapeutic resistance in the context of glioblastoma." (PMID 33765907, 2021). "Even in glioblastoma patients, HGF/tyrosine protein kinase Met (c-MET) pathway was highly upregulated during the recurrence after bevacizumab treatment." (PMID 32456056, 2020). "We found that APC- and biotin-conjugated anti-MET antibodies strongly induced MET and AKT phosphorylation, as compared to the HGF control, in all these glioblastoma cell lines." (PMID 30760737, 2019). "In glioblastoma, we identified an RND1low signature of six genes (ITGA5, COL3A1, COL5A1, MET, COL1A2, LAMC1), upregulated in glioblastoma patients with low RND1, that predicts the overall survival of glioblastoma patients." (PMID 31344837, 2019). "RTK genes are frequently altered in glioblastomas; in fact, at least one RTK is altered in 65–75% of glioblastomas (EGFR (50–58%), PDGFRA (12–15%), MET (2–3%), and FGFR2/3 (3%))." (PMID 30279357, 2018). "MET and MDM2 amplifications were seen in 3 out of 78 (3.8%) and 17 out of 110 cases (15.5%) molecular glioblastomas respectively tested for these amplifications." (PMID 30470264, 2018). "Regulation of MET expression by TGFβ1 seems to be tumor‐type‐specific as in glioblastoma, TGFβ suppresses HGF/MET pathway activity." (PMID 30004628, 2018). "MET and TGFBR2 gene expressions were found to positively correlate in several other tumor entities, such as prostate adenocarcinoma, thymoma, glioblastoma, head and neck squamous cell carcinoma, testicular germ cell tumors, and esophageal carcinoma." (PMID 30004628, 2018). "We co-stained glioblastoma tissue samples from a large cohort of 66 different glioblastoma patient for TGF-β2 (red) and p-c-MET (green)." (PMID 29238047, 2017). "The aim of this work was to study the targets of crizotinib: ALK, ROS1, and MET by using IHC, FISH, and direct sequencing in nine GSC lines derived from nine glioblastoma samples." (PMID 28960893, 2017).